TNF (tumor necrosis factor)
Diseases named in the same sentence as TNF in open-access papers (continued):
Sharing a sentence is not in itself a finding about the gene and the disease.
Sepsis (continued). "The significant contribution of the TNF-α to the pathology of the inflammatory response generated the idea of a possible genetic determinism of its circulating levels and hence of sepsis risk and evolution." (PMID 32171247, 2020). "Further, marked increases in TNFα have been linked to a higher rate of mortality in cases of equine colic and sepsis in foals." (PMID 30931316, 2019). "Thrombocytopenia in septic patients and platelet depletion in mouse models of sepsis is associated with mortality, and the loss of platelets can drive an elevation in plasma pro-inflammatory cytokines (TNFα and IL-6) in septic mice." (PMID 31581214, 2019). "According to previous reports, the dysregulated expression of the cytokines, IL-6, TNF-α, and IL-1β, is associated with mortality in patients with sepsis." (PMID 31333903, 2019). "Clinical and experimental studies indicated that cardiac dysfunction is closely associated with the release of inflammatory cytokines in sepsis, and cardiac function can be improved via decreasing TNF-α level in septic animal model and patients with sepsis." (PMID 31315617, 2019). "TNFα directly stimulates hepatocytes to produce IL-6, the major mediator of acute phase response, which is known to be increased in sepsis patients and associated with a higher risk of death." (PMID 30873161, 2019). "Pro-inflammatory cytokines, such as interleukin (IL)-6, IL-1β, and tumor necrosis factor (TNF) α have been shown to contribute to sepsis-associated hepatocellular dysfunction." (PMID 30873161, 2019). "TNF signaling pathway is intimately implicated in the innate immune response in the development of sepsis." (PMID 31093495, 2019). "In line with these previous studies, we discovered that high expression of lncRNA ITSN1‐2 was associated with increased APACHE II score, CRP, TNF‐α, IL‐6, and IL‐8 levels in sepsis patients." (PMID 30803045, 2019). "One of the most significantly upregulated cytokines following infection with all five strains was TNF-α, a potent pyrogen that can induce cell death and has been linked to tissue damage and sepsis previously." (PMID 31536604, 2019). "Regarding inflammation, lnc‐THRIL was positively associated with CRP, PCT, TNF‐α, and IL‐1β levels in sepsis patients." (PMID 31257645, 2019). "Some researchers found that the TNF-α level significantly increased in patients with sepsis caused by severe burns and was positively correlated with serum myocardial enzymes." (PMID 30402132, 2018). "Several studies demonstrate that TNF serum levels in sepsis patients are elevated and associated with mortality and they are used as effective markers in the diagnosis of neonatal sepsis." (PMID 29751683, 2018). "NF-κB signaling is involved in regulating the transcription of sepsis related immunomodulatory mediators associated with the onset of sepsis-triggering organ failure such as TNF-α, IL-6 and iNOS34." (PMID 30297806, 2018). "Patients who suffer from burns, post-major surgery, and those with sepsis have been reported to have increased IL-6 levels, and the peak IL-6 level is associated with the concentration of TNF-α." (PMID 30142934, 2018). "ZmpB causes an increase in tumor necrosis factor-alpha (TNF-α) concentration, which can exacerbate the severity of pneumococcal pneumonia and septicemia." (PMID 30538741, 2018). "Recently, several association studies have shown that the TNF-α polymorphisms were related to the susceptibility to various specific infections, including pulmonary tuberculosis, leprosy, severe sepsis in trauma patients, HBV, and HIV." (PMID 29939989, 2018).
Sepsis (continued). "Further support for the positive association between sepsis severity and immunosuppression are provided by reports of increased mortality in septic patients with elevated IL-10 levels or a high IL-10/TNFα ratio." (PMID 30555806, 2018). "High levels of TNF-α and IL-6 are associated with worse prognoses in septicemia and progression and worsening of RA." (PMID 29924840, 2018). "It was detected that various genetic polymorphisms, including TNF-α, IL-1, IL-6, and IL- 10, were associated with a predisposition to infection and increased mortality in patients with sepsis." (PMID 28840846, 2018). "In a polymicrobial sepsis mouse model, Zn deficiency was shown to enhance bacterial burden, NF-κβ activity, and the corresponding IL1β, TNFα, and ICAM-1 gene expression and protein production in the lung when compared to Zn sufficient control animals." (PMID 30417019, 2018). "Growing evidence indicates that genetic polymorphisms in genes encoding inflammation-related cytokines, including IL-6, IL-10 and TNF-α, play significant roles in the pathogenesis of sepsis and even contribute to sepsis susceptibility and progression." (PMID 30268141, 2018). "While there is concomitant secretion of pro- and anti-inflammatory cytokines during sepsis, the increased ratio of IL-10 to TNFα is associated with sepsis mortality and immunosuppression, however, the mechanism for this association has yet to be elucidated." (PMID 30555806, 2018). "When polymicrobial sepsis was initiated by ip injection of cecal microflora, the levels of TNF were severely elevated and mice deficient for TNFR1 or both TNFRs survived the induced sepsis." (PMID 29751683, 2018). "TNF-α rs361525 was also found be slightly linked to the risk of severe sepsis or septic shock for the homozygote and recessive models." (PMID 29340067, 2017). "TNF-α rs1800629 was reported as a sepsis risk factor in severely injured North Indian patients, critically ill Japanese patients, the Chinese Han population, and Turkish children." (PMID 29340067, 2017). "Our results suggest that the G/A genotype of TNF-α rs1800629 and rs361525 increases sepsis risk in an Asian population." (PMID 29340067, 2017). "TNF-α (tumor necrosis factor-α) is important for normal body functions, but is also implicated in some disease mechanisms, including sepsis, diabetes mellitus, and cancer." (PMID 29340067, 2017). "Excessive production of inflammatory cytokines is a major cause of pathophysiology in patients with sepsis, and some of these cytokines [i.e., interleukin-1β and tissue necrosis factor-α (TNF-α)] have been implicated in CNS neurodegeneration." (PMID 29270174, 2017). "High expression of IL-10 and TNF-α correlate with poor prognostic in patients with severe sepsis whereas higher levels of TNF-α, IL-6, and soluble TNF receptor (sTNFR) are associated with early hemodynamic deterioration." (PMID 29269852, 2017). "This suggested that the TNF-α rs1800629 G/A genotype was associated with sepsis risk in the overall population." (PMID 29340067, 2017). "We only observed the potential association between TNF-α rs1800629 and severe sepsis risk for the allele, dominant, and carrier models." (PMID 29340067, 2017). "Interleukin-1β (IL-1β), IL-6, IL-10 and tumor necrosis factor-α (TNF-α) are some of the classical sepsis-associated cytokines." (PMID 28176831, 2017). "Sepsis was associated with increased TNF-α and IL-10 levels in the hypothalamus and higher IL-1β, IL-6, and IL-10 in the brainstem." (PMID 27229490, 2017). "NO and overexpressed cytokines, such as tumor necrosis factor-α (TNF-α), interleukin-1β (IL-1β), and IL-6, were also shown to cause sepsis-related systemic inflammation and myocardial depression in sepsis and septic shock." (PMID 29211014, 2017). "Combined analysis revealed an association between TNF-α -308G/A gene polymorphism and risk of sepsis (AA+GA vs. GG, OR 1.35, 95% CI 1.10–1.67, P = 0.005)." (PMID 29212277, 2017).
Sepsis (continued). "One of the key pro-inflammatory cytokines in sepsis, TNF-α, can cause T lymphocyte apoptosis, and β2-adrenergic blockade has been reported to induce splenocyte apoptosis." (PMID 28270914, 2017). "Sepsis-related hepatic dysfunction is associated with elevated plasma levels of endothelin-1, TNF-α and IL-6." (PMID 28542386, 2017). "The dominant model (AA+GA vs. GG) indicated a significant association between the TNF-α −308 A/G polymorphism and sepsis risk (OR 1.35, 95% CI 1.10–1.67, P = 0.005)." (PMID 29212277, 2017). "The -308G/A polymorphism in the gene encoding tumor necrosis factor-α (TNF-α) has been implicated in sepsis risk in many studies but with variable results." (PMID 29212277, 2017). "Numerous studies have examined various SNPs in the TNF-α gene and their potential relationship to sepsis risk." (PMID 29212277, 2017). "Our meta-analysis indicated a stronger association of the TNF-α −308 A/G polymorphism with risk of septic shock (OR 1.52, 95% CI 1.18–1.95) than with risk of sepsis (OR 1.35, 95% CI 1.10–1.67)." (PMID 29212277, 2017). "This updated literature search and meta-analysis comprehensively reassessed the association between TNF-α polymorphisms and sepsis risk in Asian/Caucasian populations." (PMID 29340067, 2017). "TNF-α, one of the most studied pro-inflammatory cytokines implicated in diverse diseases, is known to contribute to sepsis." (PMID 29212277, 2017). "Since the pathogenic mechanism of sepsis involves intravascular inflammation mediated by various proinflammatory cytokines, we measured the serum levels of TNF-α and IL-6 in BALB/c mice." (PMID 27937124, 2017). "Previous studies have shown that TNF and IL-6 are the cytokines most strongly associated with sepsis." (PMID 29257842, 2017). "In the pathogenesis of sepsis, three inflammatory hallmark cytokines—Interleukin-6 (IL-6), Interleukin-1β (IL-1β), and tumor necrosis factor-α (TNF-α)—are produced by monocytes and neutrophils." (PMID 29228667, 2017). "A total of 33 studies involving 11,590 subjects evaluated relationships between the TNF-α −308 A/G polymorphism and overall risk of sepsis, which included sepsis, severe sepsis, and septic shock." (PMID 29212277, 2017). "It is also possible that, since other cytokines help to mediate sepsis, polymorphism in the TNF-α gene by itself is insufficient to significantly affect risk of sepsis-related death." (PMID 29212277, 2017). "High levels of TNF in the initial phase of sepsis have been associated with early hemodynamic deterioration." (PMID 28261486, 2017). "Our subgroup meta-analyses based on controls (HB/PB), showed that the TNF-α rs1800629 G/A genotype was linked to increased sepsis risk in both groups." (PMID 29340067, 2017). "The general finding that liver inflammation promotes LCMV production is in agreement with work showing that polymicrobial sepsis, characterized by high TNF-α and inflammation, leads to increased susceptibility to LCMV infection." (PMID 27009955, 2016). "The hypocalcemia of critically ill patients with burn injury or sepsis is associated with CASR gene upregulation by TNF-alpha and IL-1beta via kappaB elements, and by IL-6 via Stat1/3 and Sp1/3 elements in the CASR gene promoters, respectively." (PMID 27679579, 2016). "These new findings emphasize the potential usefulness of H-TL1 as a promising peptide candidate for the development of new agents to treat IBD, sepsis acute shock, and other inflammatory diseases associated with TNF-α." (PMID 27879679, 2016). "Corroborating our observations, NOS inhibition or iNOS-deficiency has been shown to exacerbate TNF toxicity in a sepsis model by downregulating IFN-γ and/ or TNF production." (PMID 26915097, 2016). "Taken together, these results showed that the defective formation of innate and immune granulomas in patients with severe sepsis was related to monocytopenia and associated with reduced production of TNF." (PMID 27441846, 2016).
Sepsis (continued). "One study demonstrated that levels of endogenous inflammatory mediators such as nitrous oxide and TNF-alpha are associated with progression to severe sepsis, shock, or death." (PMID 26908009, 2016). "Subjects homozygous for the allele A of TNF (−238) showed significantly higher risk for the development of sepsis and have more chance of death in the ICU." (PMID 26561011, 2015). "In contrast, monocytes from sepsis patients were less susceptible to LPS treatment in producing TNF-α protein than that from normal donors." (PMID 25535255, 2015). "The present study shows statistically significant association between the genotype of TNF-α and the development of sepsis and outcome." (PMID 26561011, 2015). "Increases in systemic inflammatory cytokines, such as IL-6 and TNF-α, are biomarkers for and causes of poor prognosis in sepsis." (PMID 25625512, 2015). "We observed those patients who had G to A transition (G to A) had significantly higher risk of developing sepsis and also had elevated serum levels of TNF-α." (PMID 26561011, 2015). "T cells genetically deficient for TNF production were used to determine the impact of TNF on the reduced T cell proliferation following sepsis." (PMID 26734459, 2015). "The IL-1β, TNF-α and IL-10 polymorphism frequency was significantly higher in the post traumatic septic group than in the non-sepsis and appeared to be an independent risk factor for death due to septic shock." (PMID 26561011, 2015). "On univariate logistic regression analysis, the distribution of genotypes at positions IL-1α (−889 C/T), IL-4 (−1098 T/G), IL-10 (−1082 A/G), allele A of TNF-α (−238) and allele T of IL-10 (−889) were significantly (p < 0.05) predominant in sepsis." (PMID 26561011, 2015). "In an experimental model of sepsis, high levels of TNF-α were associated with reduced expression of syndecan 1 and altered composition of hyaluronan and sialic acids." (PMID 25887223, 2015). "In conclusion, we have found that the alternations in the genotype and allele frequency of IL-1β (−511C/T), TNF-α (−308 G/A), TNF-α (−238 G/A) and IL-10 (−1082 G/A) genes are associated with an higher risk of sepsis development in trauma patients and outcomes." (PMID 26561011, 2015). "Previously published studies on sepsis show that high iNOS expression is associated with inflammatory mediators, such as TNF-α, IL-1β, NF-κB, and COX." (PMID 26174316, 2015). "Expressions masking of TNF-α was found to be linked with the degree of IL-10 presence in sepsis patients." (PMID 26561011, 2015). "Sepsis is caused by a systemic response to infection, which is characterized by elevated levels of proinflammatory cytokines such as TNF-α, IL-1β, IFNγ and IL-6 in the circulation or in inflamed tissues." (PMID 25269519, 2014). "One of the earliest identified cytokines causally linked to sepsis is tumor necrosis factor-α (TNF)." (PMID 24408224, 2014). "Particular SNVs were in discussion regarding an association for sepsis (e.g. TNF, IL6, IL10) or having an potential bias to pathobiochemical processes of inflammation (e.g. SELE)." (PMID 25299518, 2014). "During sepsis, lipopolysaccharide (LPS) is recognized as the important pathogen-associated molecular pattern responsible for stimulating TNF-α production 3,7." (PMID 24304472, 2014). "In mice with experimental sepsis the direct stimulation of the vagus nerve is associated with a dramatic reduction of inflammatory cytokines (TNF-alpha) and enhances survival." (PMID 25587344, 2014). "Serum levels of IL-6 and TNF-α are increased in systemic inflammatory response syndrome and sepsis patients and are associated with increased mortality." (PMID 24651840, 2014). "A strong association had been confirmed between TNF-α polymorphisms and the clinical presentation or outcome in patients with sepsis and septic shock." (PMID 24729914, 2014).
Sepsis (continued). "In contrast, some studies, especially by Pickler and colleagues, reported that high levels of TNF-α, IL-6, and IL-1 are often associated with profiles of sepsis in neonates." (PMID 25614712, 2014). "As an immunomodulator, visfatin induces dose-dependent up-regulation of the pro- and anti-inflammatory cytokines, IL-1β, IL-6, IL-10, and TNF-α in human monocytes: visfatin is associated with sepsis, acute lung disease, atherosclerosis, and cancer." (PMID 24885580, 2014). "Based on previous research, it was shown that homozygous mutant mice for Bag4 have enhanced cytokine responses and increased IL-6 production following TNF challenge i.e. septic shock (Kp is a major pathogenic cause of sepsis)." (PMID 25283706, 2014). "It is well known that proinflammatory cytokines are implicated in the pathogenesis of sepsis, a notable example being tumor necrosis factor-alpha (TNF-α)." (PMID 24303157, 2013). "The connection between phenotype and sepsis has been established by genetic mapping of the single nucleotide polymorphisms of IL-6, IL-18, TNF-alpha, IFN-gamma, and TLRs." (PMID 24371374, 2013). "Corresponding in vitro experiments revealed that sepsis-associated mediators, such as thrombin, LPS or Tumor Necrosis Factor-α alone were sufficient to rapidly decrease eGC thickness (-50%, all P<0.0001) and stiffness (-20% P<0.0001) on HPMEC." (PMID 24278345, 2013). "Overproduction of TNF-α and IL-1β leads to tissue damage, multiple organ failure, and finally causes lethal sepsis." (PMID 24260470, 2013). "In the 1990s, sepsis was believed to be associated with an exacerbated release of mainly proinflammatory cytokines, such as tumor necrosis factor (TNF)-α, interleukin (IL)-1, IL-6, IL-12, interferon (IFN)-γ, and macrophage migration inhibitory factor (MIF)." (PMID 23853427, 2013). "Our results suggest that MMP13 is a potential therapeutic target for treatment of inflammatory disorders associated with TNF-dependent dysfunction of the intestinal barrier, such as sepsis and IBD." (PMID 23723167, 2013). "Excessive TNF-α production contributed to lung injury in a variety of diseases and increased the risk of sepsis." (PMID 23577187, 2013). "Pro-inflammatory mediators, including TNF-α and IL-1β have been implicated in the pathogenesis of myocardial dysfunction and cardiomyocyte death in ischemia-reperfusion injury, sepsis, chronic heart failure, viral myocarditis, and cardiac allograft rejection." (PMID 24287918, 2013). "In conclusion, our results suggest that MMP13 is a potential therapeutic target for treatment of inflammatory disorders associated with TNF-dependent dysfunction of the intestinal barrier, such as sepsis and IBD." (PMID 23723167, 2013). "High levels of TNF and IL-6 are associated with septic shock, however, the levels in C. albicans-infected Lat2−/− mice are much lower than those in murine sepsis models making it an unlikely cause for the increased mortality." (PMID 23675302, 2013). "In sepsis patients Trem-1 expression on neutrophils was associated with the IL-10 (LPS: r = 0,61, p < 0.02) and TNF-α inducibility (LPS: r = 0,78, p < 0,002)." (PMID 23414215, 2013). "While, ω-3 PUFA supplementation protected against severe colitis, these mice suffered greater mortality associated with sepsis-related serum factors such as LPS binding protein, IL-15 and TNF-α." (PMID 23405155, 2013). "Apoptosis occurs through inflammatory cytokines and TNFα, apoptosis-associated proteins and ROS-mediated pathways during sepsis." (PMID 23837035, 2013). "On the other hand, proinflammatory cytokines, such as TNF-α and IL-1β, have been implicated in ventricular dysfunction associated with sepsis." (PMID 24371817, 2013). "The proinflammatory cytokine tumor necrosis factor-alpha (TNF-α) is associated with myocardial dysfunction observed in sepsis and septic shock." (PMID 24303157, 2013).